OR52N1 (olfactory receptor family 52 subfamily N member 1)
Description:
Odorant receptor.
Synonyms: OR11-61
Tractability: Antibody: UniProt places it where antibodies can reach, with medium confidence; UniProt predicts a signal peptide or a membrane-spanning region; its Gene Ontology location is reachable by antibodies, with medium confidence.
Gene: Protein-coding gene on chromosome 11 (5,786,471 to 5,791,265, reverse strand). Ensembl gene ENSG00000181001.
Subcellular location: Cell membrane
Pathways (Reactome):
Sensory Perception: Expression and translocation of olfactory receptors
Gene Ontology:
Molecular function: olfactory receptor activity
Biological process: detection of chemical stimulus involved in sensory perception of smell; G protein-coupled receptor signaling pathway; nervous system process
Cellular component: plasma membrane; membrane
Genetic constraint (gnomAD): Loss-of-function variants: 9 observed, 11.75 expected, observed/expected ratio (o/e) 0.77, 90% interval 0.46 to 1.33. The upper end of that interval is the gene's LOEUF score, 1.33, which puts it in group 5 of 6, group 1 being the genes least tolerant of losing a copy. Missense variants: 368 observed, 349.87 expected, observed/expected ratio (o/e) 1.05, 90% interval 0.96 to 1.15. Synonymous variants: 124 observed, 127.21 expected, observed/expected ratio (o/e) 0.97, 90% interval 0.84 to 1.13.
Homologues: Orthologues: chimpanzee OR52N1 (98% identical), dog OR52N1 (91% identical), rabbit OR52N1 (89% identical), rat Or52n1 (87% identical), mouse Or52n1 (87% identical), rat Or52n1b (82% identical), tropical clawed frog or52ak1a (46% identical), tropical clawed frog or52ak1b (46% identical), tropical clawed frog or52ak1 (46% identical), tropical clawed frog or52k1 (46% identical). Paralogues in human: OR52N2 (75% identical), OR52N4 (72% identical), OR52N5 (69% identical), OR52D1 (49% identical), OR52A5 (48% identical), OR52E2 (48% identical), OR52E4 (48% identical), OR52R1 (48% identical), OR52E8 (48% identical), OR52E5 (47% identical), OR52E6 (47% identical), OR52K1 (47% identical), and 39 more.